FOXM1 (forkhead box M1)
Diseases named in the same sentence as FOXM1 in open-access papers (continued):
Sharing a sentence is not in itself a finding about the gene and the disease.
pancreatic cancer (continued). "Furthermore, FOXM1 engages in interactions with the signaling cascades regulating pancreatic cancer stem cells, eliciting the up-regulation of cell surface biomarkers such as CD44 and EpCAM." (PMID 39022126, 2024). "Furthermore, STAT1 inhibits the expression of FOXM1 in pancreatic cancer cells, thereby promoting gemcitabine-induced apoptosis." (PMID 39551792, 2024). "Thus, targeting the FOXM1–HGF/MET axis is considered an opportunity to develop new anticancer drugs for pancreatic cancer." (PMID 39594778, 2024). "A recent report showed that OTUB1 may accelerate metastasis of pancreatic cancer by inhibiting FOXM1 degradation." (PMID 38653740, 2024). "Also, FOXM1 plays crucial functions in aerobic glycolysis in pancreatic cancer via transcriptional regulating LDHA function." (PMID 37159818, 2023). "Diarylheptanoids can also suppress FOXM1 expression, suppressing Gli1 in pancreatic cancer cells." (PMID 36661515, 2023). "Furthermore, the expression pattern of HMGA1 and FOXM1 showed a significant strong positive correlation in most type of cancers, especially lung adenocarcinoma, pancreatic cancer and liver cancer." (PMID 37240870, 2023). "Indeed, by analyzing TCGA expression data in pancreatic cancer (PAAD dataset) we evidenced that FOXM1 high level is significantly related with bad overall survival, disease free survival and with chemotherapy response in PDAC patients." (PMID 35241126, 2022). "Furthermore, Jab1/CSN5 promotes pancreatic cancer invasion and metastasis by stabilizing a Fos family protein [Forkhead box M1 (FOXM1)]112." (PMID 35315259, 2022). "In previous research, TST has been reported to inhibit FOXM1 and the malignant behaviour of a variety of tumours, including colorectal cancer, breast cancer, lung cancer, acute lymphoblastic leukaemia, ovarian cancer, and even pancreatic cancer." (PMID 35859150, 2022). "MiR-320b suppresses pancreatic cancer cell proliferation through regulating FOXM1." (PMID 35799265, 2022). "Additionally of interest in this regard was a recent report that domatinostat reduced the protein levels of FOXM1 in pancreatic cancer cells, which reportedly plays a crucial role in the maintenance of GSCs." (PMID 35897656, 2022). "To this end, we analyzed the expression of FOXM1 and all miRNAs in public TCGA database and found miR-552, which could be the most relevant miRNA with FOXM1 in pancreatic cancer." (PMID 33867818, 2021). "Indeed, in our pancreatic cancer transcriptomic dataset, both FOXM1 and MYBL2 were robustly Wnt‐activated." (PMID 33660437, 2021). "Interestingly, FOXM1 (B) has been demonstrated to promote the Warburg effect in pancreatic cancer by increasing LDHA transcription." (PMID 33314660, 2021). "In a pancreatic cancer tissue microarray, miR-552 expression was positively correlated with FOXM1 and high expression of miR-552 could predict poor patient outcome." (PMID 33867818, 2021). "However to date, the effects of FOXM1 on miRNA expression in pancreatic cancer development and progression remain to be clarified." (PMID 33867818, 2021). "FoxM1 regulates cell migration and invasion of pancreatic cancer cells." (PMID 32429421, 2020). "Furthermore, STAT1 was found to be an inhibitor of Forkhead Box protein M1 (FoxM1) that acts as an oncogene via NF-κB signaling in pancreatic cancer." (PMID 32823814, 2020). "In addition, consistent with previous reports in pancreatic cancer, we also observed inhibition of migration and invasion by FoxM1 downregulation that was induced by TPGS treatment in HCC cells." (PMID 31986488, 2020). "FoxM1 is an oncogenic transcription factor that plays important roles in the initiation, progression, metastasis, and drug resistance of a variety of human tumors, including pancreatic cancer." (PMID 32429421, 2020). "Taken together, our results suggested that FOXM1 overexpression could increase the activation of the NF-κB signaling cascade in pancreatic cancer cells treated with gemcitabine." (PMID 30782607, 2019).
pancreatic cancer (continued). "Therefore, targetting FOXM1 would be a promising strategy to increase the chemotherapeutic effect of gemcitabine in pancreatic cancer." (PMID 30782607, 2019). "In conclusion, we show here for the first time that OPN promotes the EMT and CSC‐like properties of PCCs by activating the integrin αvβ3‐Akt/Erk‐FOXM1 cascade in a paracrine manner, suggesting that targeting the tumor microenvironment represents a promising therapeutic strategy in pancreatic cancer." (PMID 30367545, 2019). "Next, we investigated the regulatory mechanism of FOXM1 in pancreatic cancer and colon cancer." (PMID 30628173, 2019). "However, the role of FOXM1 in advanced pancreatic cancer, especially the development of acquired chemoresistance against chemotherapeutic agents such as gemcitabine, has not yet been determined." (PMID 30782607, 2019). "Thus, we focused on FOXM1c (hereafter referred to as FOXM1) as it was previously reported to be highly expressed in pancreatic tumors and to promote EMT and metastasis." (PMID 31072351, 2019). "Therefore, blocking STAT1/FOXM1/NFkB axis by interferon γ (IFNγ) can increase the sensitivity of pancreatic cancer to gemcitabine." (PMID 30782607, 2019). "Immunohistochemical analysis demonstrated a negative association of FOXM1 expression and the level of phosphorylated signal transducer and activator of transcription 1 (pSTAT1) in human pancreatic cancer tissues." (PMID 30782607, 2019). "In addition, as an oncogene that drives pancreatic cancer development and chemotherapy resistance, FOXM1 should be more and more valued by doctors and researchers as therapeutic targets." (PMID 30782607, 2019). "Since histone methylation is modified by the histone methyltransferase, we next examined the clinical relevance of histone methyltransferase (MLL1, MLL2, MLL3, MLL4, SET1A, SET1B for H3K4me3 and DOT1L for H3K79me2) and FOXM1 in pancreatic cancer and colon cancer." (PMID 30628173, 2019). "By positively regulating oncogenes such as VEGF and B‐cell lymphoma 2 (BCL‐2), FOXM1 impacts tumor initiation, angiogenesis, progression, drug resistance, and metastasis in prostate cancer, hepatocellular carcinoma, pancreatic cancer, colon cancer, breast cancer, and glioblastoma." (PMID 30628173, 2019). "In glioblastoma, as well as in pancreatic cancer FoxM1 is critical for Wnt/b-catenin signaling." (PMID 28387346, 2017). "Furthermore, a recent study found that FOXM1 played important roles in aerobic glycolysis and tumorigenesis in patients with pancreatic cancer via transcriptional regulation of lactate dehydrogenase A (LDHA) expression." (PMID 27351131, 2016). "Moreover, amplifications of FOXM1 gene have been demonstrated in several tumors such as hepatocellular cancer, pancreatic cancer, and glioblastoma multiforme tumors." (PMID 24918286, 2014). "However, the molecular mechanisms by which FOXM1 signaling regulates PCSCs in pancreatic cancer development and progression remain poorly understood." (PMID 24325450, 2013). "Furthermore, researchers have proposed that Forkhead box protein M1 (FOXM1) is involved in the self-renewal of PCSCs, and tumorigenesis and metastasis of pancreatic cancer cells." (PMID 24325450, 2013). "Therefore, inhibition of FoxM1 represents a therapeutic strategy for treating pancreatic cancer." (PMID 32429421, 2020). "Our further analysis showed that OPN and FOXM1 are significantly upregulated in pancreatic cancer tissues and are associated with poor clinical outcome, indicating that OPN and FOXM1 might be considered as diagnostic and prognostic biomarkers for patients with pancreatic cancer." (PMID 30367545, 2019). "Therefore, FOXM1 might represent a novel target for sensitizing therapy in gemcitabine-based chemotherapy of pancreatic cancer." (PMID 30782607, 2019).
pancreatic cancer (continued). "In addition, down-regulation of FOXM1 expression could enhance the sensitivity to chemotherapy in vitro, which indicated that knockdown of FOXM1 expression enhanced chemosensitivity of pancreatic cancer cells to gemcitabine." (PMID 30782607, 2019). "Nevertheless, the relationship between OPN and FOXM1 in pancreatic cancer still remains unknown." (PMID 30367545, 2019). "To further determine whether the enhanced sensitivity to gemcitabine after FOXM1 inhibition correlated with changes in NF-κB activity in pancreatic cancer cells, we compared the status of NF-κB in pancreatic cancer cells using immunoblotting and NF-κB-dependent reporter activity." (PMID 30782607, 2019). "HIF-1α -Snail signaling pathway and FOXM1 are reported to induce epithelial-mesenchymal transition (EMT), which is involved in the metastasis and infiltration of pancreatic cancer." (PMID 40063301, 2025). "FOXM1 upregulation raised LDHA levels, glucose utilization, and lactate production and facilitated pancreatic cancer cell growth." (PMID 39060874, 2024). "LINC00857 upregulates FOXM1 expression and serves as a scaffold that enhances the interaction between FOXM1 and OTUB1, thus preventing deubiquitination of FOXM1, favoring FOXM1 accumulation, and leading to EMT and metastasis in pancreatic cancer." (PMID 37381723, 2023). "FOXM1 upregulated LDHA expression by promoting its transcription and was further attributed to pancreatic cancer cell proliferation and metastasis." (PMID 33777804, 2021). "This upregulation of miR-552 induced by FOXM1 further inhibited the expression of three downstream targets DACH1, PCDH10, SMAD4, which are known as tumor suppressors in pancreatic cancer progression." (PMID 33867818, 2021). "Meanwhile, the positive correlation between FOXM1 and miR-552 was verified by IHC and ISH staining in a pancreatic cancer tissue microarray." (PMID 33867818, 2021). "To further understand the role of miR-552 in FOXM1-mediated pancreatic cancer cell migration, we introduced miR-552 mimics into PANC1 and AsPC1 cells with FOXM1 knockdown." (PMID 33867818, 2021). "To elucidate the correlation between miR-552 and FOXM1 in clinical samples, we detected the expression of FOXM1 and miR-552 by immunohistochemical staining and in situ hybridization (ISH) in a pancreatic cancer tissue microarray, respectively." (PMID 33867818, 2021). "Recent reports have shown that FOXM1 contributes to pancreatic cancer invasion and progression by increasing the expression of MMP-9, MMP-2 and VEGF and downregulated FOXM1 expression results in the inhibition of pancreatic cancer cell growth and invasion." (PMID 33867818, 2021). "Forkhead protein 1 (FoxM1) has also been correlated with PTX resistance in human pancreatic cancer, through a pathway involving the overexpression of Prohibitin 1 (PHB1) and activation of the FoxM1/PHB1/RAF-MEK-ERK pathway." (PMID 33348838, 2020). "In the present study, we aimed to investigate the relationship between paracrine OPN signaling and FOXM1 and to further elucidate their contribution to the tumor–stroma interaction‐mediated EMT and stemness of tumor cells in pancreatic cancer." (PMID 30367545, 2019). "In this study, we examined the central role of FOXM1 in regulating bone marrow‐derived dendritic cell (BMDC) maturation phenotypes and function in pancreatic cancer and colon cancer." (PMID 30628173, 2019). "FOXM1 directly influences epithelial-mesenchymal transition (EMT) and pancreatic cancer cell invasion and metastasis and contributes to paclitaxel resistance in breast cancer through regulation of its target gene KIF20A." (PMID 31072351, 2019). "Therefore, our results reveal that upregulation of FOXM1 by H3K79me2 in pancreatic cancer and colon cancer significantly inhibits maturation phenotypes and function of BMDCs through the Wnt5a signaling pathway, and thus provide novel insights into FOXM1‐based antitumor immunotherapy." (PMID 30628173, 2019).
pancreatic cancer (continued). "Here, we identified a paracrine OPN/integrin αvβ3/FOXM1 cascade that modulates the EMT and CSC‐like properties of pancreatic cancer, providing a promising therapeutic target for patients with pancreatic cancer." (PMID 30367545, 2019). "After establishing the pancreatic cancer PDX models successfully as described in ‘Materials and methods’ section, three PDX models with different FOXM1 level were selected to carry out experiments." (PMID 30782607, 2019). "Taken together, our results indicate the complicated processes of the OPN/integrin αvβ3/FOXM1 cascade‐mediated EMT and CSC‐like properties in pancreatic cancer." (PMID 30367545, 2019). "Furthermore, considering that H3K79me2 enrichment of the FOXM1 promoter was detected in additional cell and tissue types, outside of the BMDCs, and pancreatic cancer and colon cancer cells addressed in this study, we suggested that similar mechanisms might broadly be applicable to other tissues." (PMID 30628173, 2019). "For example, miR-494 negatively regulates the expression of FOXM1, and miR-145 inhibits the expression of MUC13, to inhibit the proliferation, invasion, and metastasis of pancreatic cancer." (PMID 27494897, 2016). "GEN also has the potential to attenuate FOXM1-mediated cell growth, migration and invasion, the acquisition of an EMT phenotype, and CSC self-renewal capacity in pancreatic cancer cells." (PMID 24959264, 2014). "It has also been reported that the overexpression of FOXM1 leads to epithelial-mesenchymal transition (EMT) and a CSC phenotype in pancreatic cancer cells." (PMID 24959264, 2014). "A previous study reported that the overexpression of FOXM1 leads to EMT and the formation of a cancer stem cell phenotype in pancreatic cancer cells." (PMID 24959264, 2014). "Recent studies also find that FOXM1 upregulates LDHA transcription to enhance lactate production and promote cancer growth and metastasis, whereas KLF4 negatively regulates LDHA gene expression and is involved in the progression of pancreatic cancer." (PMID 39930542, 2025). "Subsequently, we quantified the expression levels of miR-23a in pancreatic tumor samples exhibiting negative/weak, moderate, and strong FOXM1 expression through laser-assisted microdissection-coupled quantitative PCR." (PMID 39022126, 2024). "The expression levels of miR-23a-3p and -5p in human pancreatic tumor specimens with strong FOXM1 expression (n = 10) were significantly lower than those with negative/weak (n = 10) and moderate FOXM1 expression (n = 10)." (PMID 39022126, 2024). "In another study, a reduction in G0/G1-phase cells and an increase in S-phase cells were observed in pancreatic cancer cells with ectopic expression of USP28, and this advancement in cell proliferation was mediated by the deubiquitination of Forkhead box M1 (FOXM1), which is induced by USP28." (PMID 36879346, 2023). "FOXM1 total expression was dramatically upregulated in pancreatic cancer, however, FOXM1a expression did not increase significantly." (PMID 37759731, 2023). "Two homeoboxes Through activities on the Fork head Box M1 (FoxM1) protein, A pseudogene 8 (DUXAP8), a pseudogenederived lncRNA, may promote pancreatic cancer, non-small-cell lung cancer, and HCC." (PMID 38274225, 2023). "Double homeobox A pseudogene 8 (DUXAP8), a pseudogene‐derived lncRNA, may play a promoting role in pancreatic cancer, non‐small‐cell lung cancer, and HCC through actions on the Fork head Box M1 (FoxM1) protein." (PMID 37337470, 2023). "In addition, TST has been indicated to be a selective inhibitor of FOXM1; therefore, we used two concentrations of TST (2 and 5 μM) to treat pancreatic cancer cells." (PMID 35859150, 2022). "Although the role of FOXM1 in pancreatic cancer chemoresistance has not been explored in detail, previous studies in other tumor types suggested that FOXM1 can promote resistance by removing ROS, enhancing DNA damage repair and influencing tumor stemness." (PMID 35241126, 2022).
pancreatic cancer (continued). "In pancreatic cancer, over-expressed ubiquitin carboxyl-terminal hydrolase L3 (UCHL3) was reported to stabilize Forkhead box protein M1 (FOXM1), which activates the transcription of LDHA, and promotes aerobic glycolysis of pancreatic cancer through the UCHL3-FOXM1-LDHA axis." (PMID 35307036, 2022). "Additionally, UCHL3 deubiquitinates and, therefore, stabilizes forkhead box M1 (FOXM1), a key transcription factor and regulator of cell cycle progression in pancreatic cancer leading to cancer progression." (PMID 35053210, 2022). "As FOXM1 was overexpressed in BMDCs from TBM, we hypothesized H3K79me2‐FOXM1 regulated innate immune cells in pancreatic cancer and colon cancer." (PMID 30628173, 2019). "IFNγ could be used to down-regulate the expression of FOXM1 through STAT1 phosphorylation, thereby increasing the sensitivity of pancreatic cancer cells to gemcitabine." (PMID 30782607, 2019). "Beyond the mechanisms described, the molecular basis of FoxM1 dysregulation has been also related to the capability of vitamin D receptor (VDR)/FoxM1 axis to affect cell stemness and to induce an invasive and metastatic phenotypes in pancreatic cancer." (PMID 28770020, 2017). "But FOXM1 expression is not statistical correlation with survival of esophageal cancer and pancreatic cancer." (PMID 28427178, 2017). "In addition, downregulation of FOXM1 induced pancreatic cancer cells to use mitochondrial respiration rather than aerobic glycolysis in high-glucose medium, further linking FOXM1 to the glycolytic pathway." (PMID 34205406, 2021). "However, there is no report of a correlation between FOXM1 and chemotherapy resistance in pancreatic cancer cells." (PMID 30782607, 2019).